LINC00665 (long independently transcribed non-coding RNA 665)
Synonyms: CIP2A-BP
Gene: Long non-coding RNA gene on chromosome 19 (36,259,540 to 36,331,770, reverse strand). Ensembl gene ENSG00000232677.
Diseases named in the same sentence as LINC00665 in open-access papers:
LINC00665 is named in the same sentence as 39 diseases in open-access papers, as found by Europe PMC text mining. Sharing a sentence is not in itself a finding about the gene and the disease. The quoted sentences say what the papers report.
breast carcinoma (26 papers, 2020 to 2024). "LINC00665 has been shown to be over-expressed in breast cancer tissue samples in association with poor prognosis of breast cancer patients." (PMID 36429005, 2022). "In breast cancer and prostate cancer, high expression of LINC00665 was also associated with the advanced TNM stage." (PMID 35563845, 2022). "The association between over-expression of LINC00665 and poor survival of patients has been verified in breast cancer, cholangiocarcinoma, gastric cancer, glioma, hepatocellular carcinoma, lung cancer, osteosarcoma, ovarian cancer, and prostate cancer." (PMID 36429005, 2022). "Upregulated LINC00665 was also significantly associated with lower disease-free survival in patients with multiple cancers, including breast cancer, prostate cancer, ovarian cancer, cholangiocarcinoma, non-small cell lung cancer, and lung adenocarcinoma." (PMID 35563845, 2022). "In reproductive system tumors, LINC00665 was significantly positively associated with larger tumors and lymph node metastases in breast cancer, prostate cancer, and ovarian cancer." (PMID 35563845, 2022). "LINC00665 is a promising diagnostic biomarker for breast cancer, gastric cancer, and hepatocellular carcinoma." (PMID 35563845, 2022). "The impact of LINC00665 in induction of expression of LIN28B is associated with induction of progression of breast cancer and activation of epithelial–mesenchymal transition (EMT) program in these cells." (PMID 36429005, 2022). "As a concerned lncRNA associated with human disease, LINC00665 was reported to increase dramatically in cell models of cerebral ischemia–reperfusion injury, and it was also enhanced in numerous tumors such as breast cancer and prostate cancer." (PMID 38167456, 2024). "LINC00665 is closely associated with the effects of anticancer drugs, including gefitinib and cisplatin in non-small cell lung cancer, gemcitabine in cholangiocarcinoma, and cisplatin-paclitaxel in breast cancer." (PMID 35563845, 2022). "They found that miR-34a-5p was significantly downregulated in ovarian cancer tissues, and when LINC00665 was knocked down in breast cancer cells, miR-34a-5p was upregulated." (PMID 35356290, 2022). "LINC00665 is a novel lncRNA, which is abnormally expressed in various human cancers, such as lung cancer, breast cancer, prostate cancer, and glioma." (PMID 35356290, 2022). "In reproductive system tumors, LINC00665 accelerates breast cancer progression by sponging miR-379-5p, miR-3619-5p and miR-551b-5p." (PMID 35563845, 2022). "In the present research, we investigated the effect and molecular mechanism of LINC00665 as a ceRNA in breast cancer cells, and confirmed that LINC00665/miR-641/SRCAP axis regulates tumor cell survival and metastasis through EMT and AKT pathway." (PMID 35152838, 2022). "LINC00665, which is generally upregulated in breast cancer, was found to be downregulated in triple-negative breast cancer." (PMID 35563845, 2022). "The effects of LINC00665 on these features of breast cancer cells are possibly exerted through sponging miR-3619-5p." (PMID 36429005, 2022). "In breast cancer and glioma, there are different conclusions about the expression level of LINC00665." (PMID 35356290, 2022). "In breast cancer, LINC00665 also acts as an independent predictor of the efficacy of cisplatin-paclitaxel combination therapy." (PMID 35563845, 2022). "In recent years, the role of LINC00665 in tumor has been gradually discovered, especially in breast cancer." (PMID 35152838, 2022). "Expression of β-catenin has been reduced following LINC00665 silencing and miR-3619-5p up-regulation, supporting the importance of LINC00665/miR-3619-5p/β-catenin axis in the progression of breast cancer." (PMID 36429005, 2022). "Aberrant expression of LINC00665 in breast cancer, gastric cancer, and hepatocellular carcinoma can be used for disease diagnosis." (PMID 35563845, 2022).
breast carcinoma (continued). "They found that the expression of the LINC00665 was significantly upregulated in breast cancer tissues." (PMID 35356290, 2022). "In gastric cancer, breast cancer, ovarian cancer, and other cancers, abnormal upregulation of LINC00665 can promote the EMT process." (PMID 35563845, 2022). "Subsequently, they used qRT-PCR to identify LINC00665 expression in 106 pairs of breast cancer tissues and adjacent normal tissues and also proved that LINC00665 was highly expressed in breast cancer tissues." (PMID 35356290, 2022). "Our results proved that knockdown of LINC00665 inhibited the proliferation, migration and invasion and induced the apoptosis, indicating a carcinogenesis role of LINC00665 in human breast cancer." (PMID 35152838, 2022). "Studies have reported that LINC00665 played a vital role in breast cancer progression, and LINC00665 Knockdown inhibited breast cancer cells proliferation, migration, and invasion but promoted apoptosis." (PMID 35356290, 2022). "In breast cancer, upregulated LINC00665 promotes cancer progression by sponging 3 miRNAs (miR-379-5p, miR-3619-5p, miR-551b-5p)." (PMID 35563845, 2022). "In breast cancer cells, LINC00665 has been found to act as a sponge for miR-379-5p, reducing the capacity of miR-379-5p to suppress expression of Lin-28 Homolog B (LIN28B)." (PMID 36429005, 2022). "We aimed to investigated the specific role and mechanism of LINC00665 in tumor cells to deepening our understanding on the progression and metastasis of breast cancer." (PMID 35152838, 2022). "This research expands our understanding of the mechanism of LINC00665 role and provides new potential targets for bio-targeted therapy in human breast cancer." (PMID 35152838, 2022). "CIP2A-BP is a micropeptide encoded by LINC00665, and its expression in breast cancer cell lines can be downregulated by TGF-b." (PMID 35233461, 2022). "LINC00665 silencing has also suppressed proliferation, migration, and invasive features of breast cancer cells, while it enhanced apoptosis." (PMID 36429005, 2022). "SNHG16, LIN01128, RP11-834C11.4(LINC02381) and LINC00665 were all verified to be involved in various cancers, such as osteosarcoma, cervical cancer, breast cancer, gastric cancer, and hepatic cancer." (PMID 34290731, 2021). "In breast cancer, LINC00665 overexpression facilitates proliferation, migration and invasion of breast cancer cells by upregulating LIN28B and inducing EMT through ceRNA regulating of miR-379-5p21." (PMID 33436545, 2021). "Long intergenic non-coding RNA 00665 (LINC00665) has been reported to serve as an oncogene in several kinds of cancers, including gastric cancer, breast cancer, prostate cancer and colorectal cancer." (PMID 34232917, 2021). "Linc00665 is a novel long non-coding RNA that can promote the progression of breast cancer, but its value in predicting the efficacy of neoadjuvant chemotherapy (NAC) for breast cancer has not been reported." (PMID 33738251, 2021). "LINC00665, for example, is known to accelerate breast cancer progression via the miR-379-5p/LIN28B pathway." (PMID 34592879, 2021). "For example, it was reported LINC00665 promotes breast cancer progression through regulation of the miR-379-5p/LIN28B axis." (PMID 33996559, 2021). "For example, knockdown of LINC00665 significantly inhibits the growth of breast cancer cells in vitro, significantly weakens the migration and invasion abilities, reduces the expression of EMT-related genes, and promotes apoptosis." (PMID 34956895, 2021). "Studies have found that LINC00665 served as an oncogene in gastric cancer, breast cancer, prostate cancer and colorectal cancer." (PMID 34232917, 2021). "Accumulating studies have revealed the crucial role of LINC00665 in multiple cancers, including gastric cancer, breast cancer and hepatocellular carcinoma." (PMID 33878735, 2021). "Taken together, our results indicate that LINC00665 promotes breast cancer progression in a manner partly dependent on miR-379-5p sponging." (PMID 31907362, 2020).
breast carcinoma (continued). "In the current study, we demonstrated that LINC00665 promotes breast cancer cell proliferation, migration, and invasion." (PMID 31907362, 2020). "In the current study, we investigated the role of LINC00665 in breast cancer development and progression." (PMID 31907362, 2020). "Consistent with the results of previous studies in other cancers, our results provide evidence that LINC00665 is upregulated in breast cancer tissues, as evidenced by analysis of the TCGA database." (PMID 31907362, 2020). "Collectively, our results reveal that the LINC00665–miR-379-5p–LIN28B axis is a critical player in breast cancer progression and a promising target for breast cancer therapy." (PMID 31907362, 2020). "LINC00665 promoted breast cancer progression and induced an epithelial–mesenchymal transition-like phenotype via the upregulation of LIN28B expression." (PMID 31907362, 2020). "Together, these results suggest that LINC00665 induces an EMT-like phenotype in breast cancer cells." (PMID 31907362, 2020). "Taken together, our results indicate that LINC00665 promotes breast cancer progression through regulating the miR-379-5p/axis." (PMID 31907362, 2020). "We propose a model that highlights the function of LINC00665 in regulating EMT during breast cancer progression." (PMID 31907362, 2020). "Additionally, LINC00665 is an emerging cancer biomarker, including in glioma and alcohol-related cancers (e.g., breast cancer and liver cancer)." (PMID 37217680, 2023). "Similarly, although LINC00665 functions as a pro-tumor factor in breast cancer (BC), its small peptide CIP2A-BP can lead to suppressed abilities of migration and invasiveness of BC cells." (PMID 37347740, 2023). "Many studies have shown that LINC00665 is involved in the progression of breast cancer as a ceRNA." (PMID 35152838, 2022). "LINC00665 promotes the survival and metastasis of breast cancer cells." (PMID 35152838, 2022). "LINC00665 is highly expressed in breast cancer tissues and promotes tumor cell survival." (PMID 35152838, 2022). "LINC00665 can also influence progression of breast cancer via sponging miR-551b-5p." (PMID 36429005, 2022). "In conclusion, LINC00665 could promote the survival and metastasis of breast cancer cells through sponging miR-641 and targeting SRCAP." (PMID 35152838, 2022). "They pointed out that LINC00665 could become a new biomarker for the prognosis of breast cancer chemotherapy." (PMID 35356290, 2022). "This confirms the diverse regulatory network of LINC00665 in breast cancer." (PMID 35152838, 2022). "LINC00665 was highly expressed in the breast cancer samples (p < 0.001)." (PMID 35152838, 2022). "In the present research, we hypothesized that LINC00665 as a ceRNA involved in the progression of breast cancer." (PMID 35152838, 2022). "Oncogenic role of LINC00665 in prostate cancer, colorectal cancer, breast cancer, and osteosarcoma." (PMID 36429005, 2022). "Then, we explored the molecular mechanism by which LINC00665 promoted breast cancer." (PMID 35152838, 2022). "All studies above directly or indirectly support the hypothesis that Linc00665 overexpression may mediate the chemo-insensitivity of breast cancer NAC through multiple pathways." (PMID 33738251, 2021). "In addition, LINC00665 is also involved in the progression of gastric cancer and breast cancer 17-19." (PMID 33613764, 2021). "In addition, LINC00665 contributes to breast cancer development via modulating miR-379-5p and LIN28B." (PMID 33407473, 2021). "All these might at least partly explain the complex interaction between Linc00665 and the ER pathway, making Linc00665 a novel predictive biomarker for breast cancer especially in HR-positive patients." (PMID 33738251, 2021). "Together, these results indicate that depletion of LINC00665 inhibits breast cancer progression." (PMID 31907362, 2020).
breast carcinoma (continued). "To demonstrate the role of LINC00665 in breast cancer development and progression, we determined the expression of LINC00665 in six breast cancer cell lines and the normal breast epithelial cell line MCF10A by reverse transcription quantitative polymerase chain reaction (RT-qPCR)." (PMID 31907362, 2020). "We next investigated whether LINC00665 regulates breast cancer progression by regulating LIN28B expression." (PMID 31907362, 2020). "We next investigated whether LINC00665 overexpression can influence cancer progression in breast cancer cells." (PMID 31907362, 2020). "Together, these results indicate that LINC00665 promotes breast cancer progression." (PMID 31907362, 2020). "LINC00665 promotes breast cancer progression and induces an EMT-like phenotype." (PMID 31907362, 2020). "Furthermore, we found that LINC00665 promotes breast cancer cell proliferation, migration, and invasion." (PMID 31907362, 2020). "Furthermore, LINC00665 functions as a ceRNA to exert malignant characteristics in breast cancer through miR-379-5p–LIN28B axis." (PMID 31907362, 2020). "In the current study, we showed that LINC00665 functions as an oncogene in breast cancer." (PMID 31907362, 2020). "In addition, LINC00665 was highly expressed in TNBC cell lines compared to that in ER+ breast cancer cell lines." (PMID 31907362, 2020). "In conclusion, we demonstrated that LINC00665 functions as an oncogene in breast cancer." (PMID 31907362, 2020). "In this study, LINC00665 reduced the expression of E-cadherin and induced the expression of N-cadherin and vimentin, whereas knockdown of endogenous LINC00665 produced the opposite effects in breast cancer cells, suggesting that LINC00665 is an inducer of EMT in breast cancer." (PMID 31907362, 2020). "More interestingly, LINC00665 can encode a special micropeptide (CIP2A-BP) to inhibit the progression of three negative breast cancers or act as a ceRNA that is involved in regulating the LINC00665/AGTR1/miR-34a-5p axis and other biological behaviours in glioma." (PMID 35174152, 2022). "They found that in breast cancer cells and mouse tumor tissues with high expression of LINC00665, E-cadherin was downregulated, and Vimentin and N-cadherin were significantly upregulated, indicating that LINC00665 induced EMT-like phenotype in breast cancer cells." (PMID 35356290, 2022). "Up to now, long intergenic non-protein-coding RNA 665 (LINC00665) has been found to show a higher expression pattern in cancers and to be closely implicated in carcinogenesis, including breast cancer, prostate cancer, gastric cancer, colorectal cancer, and ovarian cancer." (PMID 34804162, 2021). "This implied that Linc00665 may possess the ability to promote breast cancer metastasis." (PMID 33738251, 2021). "However, the role of LINC00665 in breast cancer is still unclear." (PMID 31907362, 2020). "However, the mechanism of LINC00665 in breast cancer is unclear." (PMID 31907362, 2020). "We demonstrated that LINC00665 promotes cancer progression and induces an epithelial–mesenchymal transition (EMT)-like phenotype in breast cancer by sponging miR-379-5p." (PMID 31907362, 2020). "Together, our study reveals that the LINC00665–miR-379-5p–LIN28B axis in breast cancer and provide a novel mechanism explaining breast cancer progression." (PMID 31907362, 2020). "We demonstrate that LINC00665 is overexpressed in breast cancer, and up regulated the expression of SRCAP through sponging miR-641 to finally promote the survival and metastasis of breast cancer cells." (PMID 35152838, 2022). "The level of LINC00665 in BRCA samples (n = 1085) was significantly higher than that in breast normal samples (n = 291) (P < 0.05), indicating that LINC00665 involved in the progression of human breast cancer." (PMID 35152838, 2022). "LINC00665 is involved in tumor proliferation, invasion, drug resistance, angiogenesis, and epithelial-mesenchymal transition (EMT) as an oncogene in various tumor, including breast cancer." (PMID 34956895, 2021).
breast carcinoma (continued). "The expression of LINC00665, miR-379-5p, and LIN28B in breast cancer and normal breast tissues were obtained from the TCGA database and we found upregulation of LINC00665 and LIN28B expression and a downregulation of miR-379-5p expression in breast cancer tissues." (PMID 31907362, 2020). "In addition, LINC00665 and miR-379-5p were significantly enriched in AGO-containing microribonucleoprotein complexes by RNA immunoprecipitation (RIP) assay, suggesting that both LINC00665 and miR-379-5p bind directly to AGO2 in breast cancer cells." (PMID 31907362, 2020). "In addition, two studies also demonstrated the upregulation of LINC00665 in breast cancer, but the mechanism of action of LINC00665 was not thoroughly explored." (PMID 35563845, 2022). "Furthermore, LINC00665 expression was significantly associated with the tumor size and TNM stage, but not with the age of the breast cancer patients." (PMID 35356290, 2022). "Given the effect of Linc00665 in tumorigenesis, EMT progression and drug resistance, the investigators speculate that high expression of Linc00665 might make breast cancer insensitive to NAC, and not prone to achieve pCR." (PMID 33738251, 2021). "We further explored the effect of LINC00665 on breast cancer proliferation, migration, and invasion in vitro by introducing LINC00665 siRNAs into the MDA-MB-231 and BT549 cell lines, which have higher endogenous LINC00665 expression levels than the other breast cancer cell lines." (PMID 31907362, 2020).